ALB (albumin)
Diseases named in the same sentence as ALB in open-access papers (continued):
Sharing a sentence is not in itself a finding about the gene and the disease.
advanced heart failure (2 papers, 2021 to 2022). Patients with advanced heart failure have severe limitations, experiences symptoms even while at rest and are mostly bedbound patients. "A previous study reported that decreased albumin was a predictor of shorter survival, and lower lymphocyte concentrations were linked to greater mortality in patients with advanced heart failure." (PMID 36721568, 2022).
agranulocytosis (2 papers, 2023 to 2024). "Total protein, albumin, septic shock and agranulocytosis duration>20 days were related to the poor prognosis of AML patients after BSI." (PMID 38912203, 2024).
amenorrhea (2 papers, 2019 to 2021). The absence of menses in a woman who has achieved reproductive age. "Analysis of the data indicates that the prevalence of low serum albumin is very similar in different of amenorrhea duration, but a higher prevalence is only related to lower BMI." (PMID 33608860, 2021). "As presented by our data, the amenorrhea duration does not have an effect on nutritional alterations, and blood albumin and glycose concentration are the only parameters on which BMI showed an effect." (PMID 33608860, 2021).
ampullary adenocarcinoma (2 papers, 2023 to 2024). "We describe a case of recurrent metastatic ampullary adenocarcinoma of the pancreaticobiliary subtype treated with nanoparticle albumin-bound (nab)-paclitaxel and gemcitabine as first-line treatment." (PMID 37626821, 2023). "Similarly, in patients with ampullary adenocarcinoma undergoing radical pancreaticoduodenectomy, a high preoperative TBIL to albumin ratio was identified as an independent protective factor against recurrence." (PMID 39421169, 2024).
angioedema (2 papers, 2009 to 2017). Swelling involving the deep dermis, subcutaneous, or submucosal tissues, representing localized edema. "Patients with moderate or angioedema at any site, treated within 5 h of onset showed initial improvement after a mean (SD) of 55 (±16) min compared with 563 (±72) min for those treated with albumin placebo." (PMID 29594115, 2017).
angiosarcoma (2 papers, 2015 to 2018). A malignant tumor arising from the endothelial cells of the blood vessels. "Overexpression of serum protein acidic and rich in cysteine (SPARC), a biomarker for albumin bound paclitaxel, was seen in 35.9% of the cases, especially in over 60% of epithelioid hemangioendothelioma (EHE) and chondrosarcoma (notably conventional chondrosarcoma), as well as 48.7% of angiosarcomas." (PMID 25906748, 2015).
antibody deficiencies (2 papers, 2023 to 2024). "Calculated globulin (CG, total protein minus albumin levels) correlate well with IgG levels and has been proposed as a suitable screening method for individuals with primary antibody deficiencies (PADs)." (PMID 39507534, 2024). "CG should not be used for patients suspected of having hypogammaglobulinemia since Ig measurements are cheaper and yield conclusive results, but rather as an opportunistic screening for patients undergoing albumin and total protein measurements for other diagnoses." (PMID 39507534, 2024).
antiphospholipid syndrome (2 papers, 2022 to 2024). A disorder caused by the presence of autoantibodies directed against phospholipids, causing a hypercoaguable state, which may result in blood clots, stroke, heart attack, and in women, significant pregnancy-related complications, including miscarriage and still birth. "Antiphospholipid syndrome (APS), VTE history, a hospital stay of over 3 days, high D-dimer (D-D), and decreased serum albumin were independent risk factors for VTE." (PMID 36525417, 2022).
aortic valve calcification (2 papers, 2021 to 2022). "Aortic valve calcifications negatively correlated with albumin (r = −0.51, p = 0.021) and positively with the Pugh–Child score (r = 0.57, p = 0.008)." (PMID 35884801, 2022).
Apathy (2 papers, 2020). Apathy is a quantitative reduction of interest, motivation and the initiation and persistence of goal-directed behavior, where often the accompanying emotions, thoughts, and social interactions are also diminished. "Furthermore, a loss of albumin via kidneys or the gastrointestinal tract, gastrointestinal malabsorption, as well as reduced feed intake due to apathy, may have worsened hypoproteinemia." (PMID 33315933, 2020).
bacterial pneumonia (2 papers, 2022 to 2025). Acute infection of the lung parenchyma caused by bacteria (e.g., Streptococcus pneumoniae, Haemophilus influenzae, Chlamydia pneumoniae, Mycoplasma pneumoniae, and Legionella pneumophila). "Patients with bacterial pneumonia presented with reduced levels of albumin, hemoglobin, and lymphocytes and elevated PCT, globulin, glucose, and urea levels; WBC counts; and neutrophil ratios." (PMID 41270012, 2025).
behavioral disorders (2 papers, 2021 to 2025). "Increased food insecurity was associated with more behavioural problems in adolescents, as well as lower haemoglobin and albumin levels, faster processing speed and increased Tanner staging in boys." (PMID 34966558, 2021). "However, total bilirubin, creatinine, albumin, and mental/behavioral disorders demonstrated residual imbalances despite propensity score matching (standardized mean differences ≥0.10)." (PMID 40948345, 2025).
Behçet’s disease (2 papers, 2024 to 2026). "In conclusion, our study demonstrates that systemic inflammatory biomarkers—NLR, SII, PIV, and CRP/albumin ratio—are significantly elevated in pediatric Behçet’s disease and show strong correlations with organ-specific involvement." (PMID 41457500, 2026). "The aim of this study is to investigate the potential of C-reactive protein (CRP)/albumin (CAR) ratio as a tool for assessing the severity of Behçet’s disease." (PMID 39050391, 2024). "The CRP and albumin levels of Behçet’s disease patients who presented to our dermatology clinic over a three-year period from February 2020 to February 2022 were included, along with the identical laboratory parameters in the control group." (PMID 39050391, 2024). "In our study, a significant decrease was found in albumin levels in BD patients who only had joint complaints compared to the albumin level of Behçet’s disease patients (p < 0.05)." (PMID 39050391, 2024). "When the disease activity of Behçet’s disease patients was classified as active or inactive, CRP, albumin, and CAR were not statistically different (p = 0.081, p = 0.771, p = 0.062, respectively)." (PMID 39050391, 2024).
bilirubin encephalopathy (2 papers, 2020 to 2023). "The results from univariate regression indicated the total bilirubin/albumin ratio was positively associated with bilirubin encephalopathy (odds ratio (OR) = 1.67, 95% confidence interval (CI): 1.59–3.14)." (PMID 31950971, 2020). "After adjusting some potential cofounding factors, the total bilirubin-albumin was still associated with bilirubin encephalopathy." (PMID 31950971, 2020). "The results from univariate regression indicated that the total bilirubin/albumin ratio was positively associated with bilirubin encephalopathy (odds ratio (OR) = 1.67, 95% confidence interval (CI): 1.59–3.14)." (PMID 31950971, 2020). "Our results indicated that the bilirubin-albumin ratio is associated with bilirubin encephalopathy in neonates, and could be a potential predictor." (PMID 31950971, 2020). "The total serum bilirubin and bilirubin to albumin ratio were the most commonly used laboratory examinations to predict bilirubin encephalopathy, but their usefulness is controversial." (PMID 31950971, 2020). "The prediction and diagnosis of bilirubin encephalopathy are dependent on the assessment of clinical symptoms, total serum bilirubin, bilirubin to albumin ratio, auditory brainstem response, and magnetic resonance imaging." (PMID 31950971, 2020). "We performed the present study to summarize the recent epidemiological characteristics of bilirubin encephalopathy and assess the role of total bilirubin-albumin ratio in the bilirubin encephalopathy." (PMID 31950971, 2020).
blood pressure (2 papers, 2016 to 2025). "Adding to this complexity, the Norwegian Oslo Health Study presents an apparently contradictory finding, suggesting that increased serum albumin within the physiological range correlates with higher blood pressure." (PMID 39897307, 2025).
bone-mineral disorder (2 papers, 2016 to 2020). "These significant associations persisted after further adjustment for clinical factors related to malnutrition-inflammation-atherosclerosis (MIA) syndrome (serum albumin, CRP, and hemoglobin) (model 2) and mineral and bone disorders (MBD) (1,25-dihydroxyvitamin D3 and whole PTH) (model 3)." (PMID 27662624, 2016).
brucellosis (2 papers, 2021 to 2023). Brucellosis is a bacterial infection that spreads from animals to people via unpasteurized dairy products or by exposure to contaminated animal products or infected animals. "In brucellosis patients, albumin levels were significantly lower (34.976–0.702) than in the healthy group." (PMID 36710909, 2023).
bullous pemphigoid (2 papers, 2020 to 2022). Bullous pemphigoid (BP) is the most common form of autoimmune bullous dermatosis. "Low serum albumin levels and high erythrocyte sedimentation rate could reflect disease severity and have been considered to increase the mortality of patients with bullous pemphigoid." (PMID 35427358, 2022).
carcinoma of the tongue (2 papers, 2022). "Thereafter, a case report was published in 1990 where a patient with an inoperable carcinoma of the tongue received intra-arterially injected 211At-labeled human serum albumin microspheres as a palliative measure." (PMID 36687417, 2022). "The study aims to identify LLNs by intraoperative near-infrared (NIR) fluorescence imaging with indocyanine green absorbed into human serum albumin (ICG: HSA) and describe the presence of lymphatic drainage channels from the floor of the mouth in patients with tongue carcinoma." (PMID 36238684, 2022).
cardiac amyloidosis (2 papers, 2022 to 2024). Cardiac amyloidosis is a condition whereby cardiac tissue is infiltrated by amyloid fibrils. "When cardiac amyloidosis accumulation is detected, immunohistochemical subtyping is performed with Amyloid A, C4d, Fibrinogen, Pre Albumin/Transthyretin (TTR), Lambda, Lysozyme, and Kappa." (PMID 38111336, 2024). "There were trends that the patients with cardiac amyloidosis had lower albumin level, higher lactate dehydrogenase and alkaline phosphatase levels, but the results were not statistically significant." (PMID 36119749, 2022).
chlamydia infection (2 papers, 2024 to 2025). "Multivariate analysis confirmed winter, chlamydia infection, conjunctival congestion, fever duration, and hemoglobin, NT-proBNP, ALB, and TBIL levels as independent risk factors, suggesting that these variables may have an independent impact on the outcome variables." (PMID 41383607, 2025). "Since the detection of chlamydia infections and the measurement of monocyte, neutrophils, and albumin used different specimens, we generated group‐tested outcomes for disease presence independently." (PMID 39375883, 2024). "In this analysis, we considered using monocyte, neutrophils, and albumin as biomarkers for chlamydia infections." (PMID 39375883, 2024).
chronic GVHD (2 papers, 2021 to 2022). "Among other laboratory indicators, lower albumin is associated with disease activity in patients with chronic GvHD." (PMID 34932150, 2022).
chronic venous insufficiency (2 papers, 2024 to 2026). Chronic form of venous insufficiency (disease). "In patients with chronic venous insufficiency (CVI), a larger wound area was significantly associated with lower levels of albumin (p = 0.0126), hemoglobin (p = 0.0095), and NRI (p = 0.0115)." (PMID 39797126, 2024). "Exudate levels and severity in chronic venous insufficiency (CVI) patients and diabetic foot disease (DFD) were associated with lower hemoglobin, albumin, and NRI values." (PMID 39797126, 2024).
clear cell carcinoma (2 papers, 2010 to 2023). "Among them, 120 had clear cell carcinoma: one patient for whom the GNRI could not be calculated owing to missing serum albumin data was excluded." (PMID 37968545, 2023).
CNS lymphoma (2 papers, 2015 to 2025). "Moreover, high CSF albumin levels had better specificity for CNS lymphoma than did CSF AT III levels." (PMID 25697593, 2015).
cognitive (2 papers, 2021). "Compared to the study participants who lived with someone and had normal cognitive function, cognitively impaired persons living alone were approximately 3.1 times more likely to have a low serum albumin level and 2.8 times more likely to have a low FFMI." (PMID 34813604, 2021). "The histone deacetylase inhibitor trichostatin A increased albumin expression and Aβ clearance in APP/PS1 mice and improved cognitive deficits." (PMID 35295737, 2021).
colonic disease (2 papers, 2019 to 2025). "Interestingly, albumin-adjusted plasma free thiol concentrations were most strikingly reduced in CD patients with only colonic disease." (PMID 31080419, 2019). "Furthermore, we observed that CD patients with only colonic disease had significantly lower albumin-adjusted plasma free thiol concentrations as compared to patients with ileocolonic disease." (PMID 31080419, 2019).
colonic diverticulitis (2 papers, 2023 to 2025). "In this study, we aimed to evaluate the predictive role of albumin-based nutritional indices in the decision of surgical techniques in patients treated operatively for complicated left colonic diverticulitis." (PMID 40870500, 2025). "We investigated various markers such as NLR, LMR, PLR, CRP/albumin ratio, and mGPS to evaluate risk factors for the failure of non-operative treatment of colonic diverticulitis." (PMID 36927780, 2023).
convulsion (2 papers, 2024 to 2025). A rapid and repeated body muscle contract that results in an uncontrolled shaking of the body. "In 1843, John C. W. Lever described the presence of albumin in the urine of women with puerperal convulsions, a finding confirmed by Sir James Young Simpson, a pioneer of modern obstetrics." (PMID 41210849, 2025).
Cryptococcal meningitis (2 papers, 2023 to 2024). Meningeal inflammation produced by cryptococcus neoformans, an encapsulated yeast that tends to infect individuals with acquired immunodeficiency syndrome and other immunocompromised states. "Increased CSF protein, albumin and IgA ratio, and granulocytes mainly drove the differences between CM and HIV as well as CM and Ctrl and indicated cryptococcal meningitis." (PMID 38961320, 2024).
dental fluorosis (2 papers, 2019 to 2022). A condition that results from excessive fluoride ingestion during tooth development, resulting in tooth discoloration ranging from white streaks to brown stains and cracks or pits in the tooth enamel. "They considered that the significant decrease of serum zinc in the fluorosis patient group may be related to the increased excretion of zinc in urine, the decrease of plasma proteins, such as albumin, and the inability of albumin to transport zinc in its binding form." (PMID 35646794, 2022). "Human studies have also shown that circulating ALB levels of individuals with skeletal fluorosis as well as the concentration of salivary albumin in children with dental fluorosis are significantly lower than in healthy controls without fluorosis." (PMID 30917615, 2019).
disc degeneration (2 papers, 2022). "First, we found an accumulation of albumin and AOPPs in the disc degeneration caused by the puncture, further suggesting the involvement of AOPPs in the pathological process of disc degeneration." (PMID 35935259, 2022). "It is worth mentioning that we separately analyzed the effects of ALB and ALP on severe disc degeneration and fusion rate." (PMID 36012961, 2022).
dissection (2 papers, 2022). The separation and isolation of tissues for surgical purposes, or for the analysis or study of their structures. "The albumin and glutaraldehyde combination (Bio Glue) include the reported risks of embolization, local tissue destruction, and the bovine source of the albumin with the related risks or immunologic effects but they are useful in major aortic surgery, as aortic dissection or thoracic aneurysms." (PMID 35335519, 2022).
Down syndrome (2 papers, 2018 to 2023). "The quantification of homed human stem cells in the murine livers by Down syndrome sequence real-time PCR, as well as the human albumin IHC test, confirmed that more stem cells survived in the injured murine liver after LPA/S1P pre-treatment." (PMID 29898789, 2018).
Duchenne muscular dystrophy (2 papers, 2021). Duchenne muscular dystrophy (DMD) is a neuromuscular disease characterized by rapidly progressive muscle weakness and wasting due to degeneration of skeletal, smooth and cardiac muscle. "Of note, previous studies in mouse models of muscular atrophy and Duchenne muscular dystrophy have demonstrated high levels of serum albumin in skeletal muscle and diaphragm that correlated with muscle degeneration." (PMID 34070501, 2021).
dysentery (2 papers, 2013 to 2024). Acute inflammation of the intestine associated with infectious diarrhea of various etiologies, generally acquired by eating contaminated food containing toxins, biological derived from bacteria or other microorganisms. "When adults with infectious diarrhoea and IBD were compared, those with IBD were more likely to have abnormal platelets, albumin, WBC, haemoglobin, and ESR." (PMID 38671637, 2024).
dyspepsia (2 papers, 2013 to 2023). An uncomfortable, often painful feeling in the stomach, resulting from impaired digestion. "Another interesting result of our correlation analysis in our patients with dyspepsia was the negative correlation of serum albumin levels with anti-EMA and atrophy of the gastric mucosa." (PMID 37546692, 2023).
Ebola (2 papers, 2020 to 2024). "The genes of the variable heavy chain and variable light chain regions from human-derived anti-Ebola (HumscFv), rabbit derived anti-peptide specific antibody (RabscFv), and llama derived anti-human serum albumin (HSA) were obtained from different sources as described in method Section 2.3." (PMID 32764309, 2020).
Ecchymosis (2 papers, 2023 to 2025). A purpuric lesion that is larger than 1 cm in diameter. "Firstly, the small sample size of this study may result in the underestimation of some variables, such as older age, HBL, albumin and hemoglobin level, which were already reported as the risk factors of ecchymosis." (PMID 36769808, 2023).
egg allergy (2 papers, 2020 to 2025). A food allergy that is an allergy or hypersensitivity to dietary substances from the yolk or whites of eggs, causing an overreaction of the immune system which may lead to severe physical symptoms. "Moreover, because purified IgY does not contain the allergenic egg albumin, it can also be safely used by patients with egg allergy." (PMID 33134398, 2020).
epidural abscess (2 papers, 2022 to 2025). Circumscribed collections of suppurative material occurring in the spinal or intracranial epidural space. "Furthermore, the CRP-to-albumin ratio is a valuable metric for monitoring spinal epidural abscesses." (PMID 41031628, 2025).
esophagogastric junction adenocarcinoma (2 papers, 2025 to 2026). "Based on this rationale, we evaluated the efficacy of combining albumin-bound paclitaxel and S-1 with camrelizumab for the first-line treatment of G/GEJ adenocarcinoma." (PMID 41550955, 2025). "Thus, we conducted a clinical trial to evaluate the efficacy and safety of the combination of camrelizumab, albumin-bound paclitaxel and S-1 as first-line treatment for patients with advanced G/GEJ adenocarcinoma." (PMID 41550955, 2025). "In conclusion, the combination of camrelizumab, albumin-bound paclitaxel, and S-1 as first-line treatment for patients with HER2-negative advanced G/GEJ adenocarcinoma showed promising efficacy and an acceptable safety profile." (PMID 41550955, 2025).